ENSG00000255835 (novel protein)
Gene: Protein-coding gene on chromosome 1 (225,886,696 to 225,924,278, reverse strand). Ensembl gene ENSG00000255835.
Genetic constraint (gnomAD): Loss-of-function variants: 26 observed, 35.05 expected, observed/expected ratio (o/e) 0.74, 90% interval 0.54 to 1.03. Missense variants: 423 observed, 448.27 expected, observed/expected ratio (o/e) 0.94, 90% interval 0.87 to 1.02. Synonymous variants: 192 observed, 188.25 expected, observed/expected ratio (o/e) 1.02, 90% interval 0.91 to 1.15.